HDAC3 (histone deacetylase 3)
Diseases named in the same sentence as HDAC3 in open-access papers (continued):
Sharing a sentence is not in itself a finding about the gene and the disease.
gastric cancer (20 papers, 2014 to 2025). A primary or metastatic malignant neoplasm involving the stomach. "In gastric cancer cell models, the knockdown of HDAC3 inhibited the nuclear translocation of STAT1, impaired IFN-γ signaling, and reduced B7-H1 expression in HGC-27 cells." (PMID 40006729, 2025). "Immuno-histochemical analysis of human gastric cancer specimens demonstrated an increase in HDAC3 expression compared to benign tissues adjacent to the tumor." (PMID 34973135, 2023). "The results reveal that the invasiveness of gastric cancer cells, largely dependent on the over-expression of the C/EBPβ/NFκB/HDAC3 signaling cascade, is indispensable for the invasiveness of pathologic tissues." (PMID 34973135, 2023). "For example, targeting HDAC3 can block epithelial mesenchymal transition plasticity in gastric cancer, HDAC3 can enhance the migration and invasion properties of fibroblasts by positively affecting the epithelial mesenchymal transition process." (PMID 37553641, 2023). "This study aimed to discern the underlying mechanisms of Honokiol in preventing the metastatic dissemination of gastric cancer cells by inhibiting HDAC3 activity/expression." (PMID 34973135, 2023). "In both assays, HDAC3 silencing reduced the capacity of gastric cancer cells to migrate by more than 60%." (PMID 34973135, 2023). "• HDAC3, which is a positive regulator of metastatic gastric cancer cell growth, can be significantly inhibited by Honokiol." (PMID 34973135, 2023). "In the analysis of verified clinical samples of the omentum, distal, and lymph node metastases, high HDAC3 expression with markedly dense staining is a poor prognostic indicator in patients with gastric cancer." (PMID 34973135, 2023). "Honokiol targeting HDAC3 by ER stress cascade and mitigating the peritoneal spread of gastric cancer." (PMID 34973135, 2023). "Transwell invasion assays further revealed significant impairment of gastric cancer cells to invade through the Matrigel-coated filters when HDAC3 was silenced." (PMID 34973135, 2023). "Histopathologic investigation of human gastric cancer tissues reveals a significant correlation between HDAC3 expression and clinical stages, expressed in the TNM (Tumor-Node-Metastasis) classification." (PMID 34973135, 2023). "In gastric cancer, HDAC3 can accelerate the invasion and migration of gastric cancer cells by targeting FOXA2." (PMID 35022030, 2022). "PDCD5 can induce HDAC3 cleavage and ubiquitin-dependent proteasome degradation, which is relevant to unfavorable prognosis of gastric cancer patients." (PMID 36266728, 2022). "HDAC3 expression is upregulated in gastric cancer, while knocked down expression levels of HDAC3 have been shown to reduce gastric cancer cell proliferation." (PMID 34991620, 2022). "We have demonstrated that MBD1 promoted the progression of gastric cancer by recruiting HDAC3 to form a complex, silencing the expression of anti-tumor miR-5701, and increasing the expression of the miR-5701 targets FGFR2." (PMID 35876658, 2022). "In vitro experiments showed that HDAC3 facilitated the proliferation, migration, and invasion of gastric cancer cells by inhibiting the expression of FOXA2." (PMID 35628623, 2022). "Consistently, Lu et al21 have figured out that reduced HDAC3 inhibited xenograft tumour growth in liver cancer, and Cui et al22 have suggested that miR‐495‐3p contributed to restraining tumour growth in gastric cancer." (PMID 33048450, 2020). "HDAC3 was found to suppress the pro-apoptotic protein PUMA in gastric cancer cells which can be restored by HDACi (TSA) treatment." (PMID 31096697, 2019). "Specific anti-HDAC1 and HDAC3 small interfering RNAs (siRNAs) were transfected into GC (gastric cancer) cells, and HDAC1 and HDAC3 expression was significantly decreased." (PMID 25167886, 2014). "Overexpression of HDAC3 is reported in many cancer types, such as lung, colorectal and gastric cancer, as well as in prostate cancer." (PMID 25521755, 2014).
gastric cancer (continued). "Moreover, HDAC3 promoted gastric cancer progression by degrading FOXA2, which in turn activates the FTO/m6A/MYC signaling axis in vitro and in vivo." (PMID 40375990, 2025). "Furthermore, the downregulation of HDAC3 through gene silencing markedly blocks the metastatic capability of gastric cancer cells in nude mice, especially towards the abdominal cavity, liver, and lungs." (PMID 34973135, 2023). "The pharmacologic inhibition or gene silencing of HDAC3 could also suppress the migration and metastasis in gastric cancer cells in vitro and in vivo." (PMID 34973135, 2023). "Conceptual model showing the working hypothesis on the interaction among Honokiol, HDAC3, and ER stress in the peritoneal dissemination of gastric cancer." (PMID 34973135, 2023). "By web-based correlation, there was a markedly positive correlation between the high expression levels of HDAC3 in 876 patients with gastric cancer, using the selected parameters and run on by Kaplan–Meier plotter (KMplot.com), Probability GSE216326 dataset, or by TCGA." (PMID 34973135, 2023). "Moreover, HDAC3 is significantly over-expressed in both gastric tissues and gastric cancer cell lines." (PMID 34973135, 2023). "The findings of the current study support the hypothesis that HDAC3 plays a crucial role in suppressing gastric cancer cell metastatic dissemination, which can be modulated by Honokiol-induced ER stress." (PMID 34973135, 2023). "• Opportunities for HDAC3 inhibition may be a potential therapeutic target for preventing gastric cancer metastatic dissemination." (PMID 34973135, 2023). "Additionally, in a mouse model of gastric cancer, it was observed that HDAC3 may induce B7-H1 expression by activating the JAK/STAT1 pathway." (PMID 40006729, 2025). "By prohibiting HDAC3, metastatic dissemination of gastric cancer may be blocked." (PMID 34973135, 2023). "Similarly, the current study also revealed that HDAC3 could interact with different EMT regulators to mediate E-cadherin repression in gastric cancer cells." (PMID 34973135, 2023). "The findings here imply that overexpressed HDAC3 is a potential therapeutic target for honokiol to reverse EMT and prevent gastric cancer migration, invasion, and metastatic dissemination." (PMID 34973135, 2023). "The present study aimed to clarify the role of Honokiol in suppressing HDAC3 activation on EMT and metastasis in gastric cancer." (PMID 34973135, 2023). "The present study provides evidence to demonstrate that HDAC3 is a positive regulator of EMT and metastatic growth of gastric cancer cells." (PMID 34973135, 2023). "This study is for the first time to elucidate the role of Honokiol-induced changes in HDAC3 (Y298) site and C/EBPβ, NFκB, on EMT and on peritoneal dissemination in gastric cancer." (PMID 34973135, 2023). "Nevertheless, how HDAC3 can regulate the expression of these EMT-inducing transcription factors and Wnt/β-catenin signaling in gastric cancer cells warrants further investigation." (PMID 34973135, 2023). "In the present study, the findings suggest a crucial role for HDAC3 in suppressing E-cadherin transcription and in up-regulating mesenchymal markers during EMT in gastric cancer." (PMID 34973135, 2023). "There have been reported that histone deacetylase 2 was increased in human gastric cancer, and histone deacetylase 3 can inhibit the expression of DTWD1, which is a cancer suppressor gene in gastric cancer." (PMID 35463631, 2022). "However, the anti-EMT potential of Honokiol and its correlation with HDAC3 regulation have not been investigated in gastric cancer in vitro and in vivo." (PMID 34973135, 2023).
gastric cancer (continued). "Furthermore, specific antibody targeting Tyr (Y298) phosphorylation of HDAC3 in three gastric cancer cell lines was markedly reduced by Honokiol after 2 h treatment (early stage), but not constitutive HDAC3 per se." (PMID 34973135, 2023). "Overall, this study demonstrates that HDAC3 may be a positive regulator of EMT and tumor metastasis in gastric cancer through transcriptional repression of E-cadherin via C/EBPβ and NFκB-p65 gene regulation, which can be significantly inhibited by treatment with Honokiol or HDAC3 inhibitors." (PMID 34973135, 2023). "Thus, HDAC3 may be a potential therapeutic target for reversing EMT and tumor metastasis in gastric cancer progression." (PMID 34973135, 2023). "Additionally, a negative correlation between HDAC3 and APOC2 protein levels was observed in NSCLC and gastric cancer (GC)." (PMID 38981044, 2024).
lung cancer (20 papers, 2013 to 2025). A malignant neoplasm involving the lung. "HDAC3 can regulate the Wnt/β-catenin signaling pathway,in lung cancer study, they found that loss the expression of HDAC3 dierupted the expression of multiple Wnt ligands, resulting in a reduction of canonical Wnt activity." (PMID 34991620, 2022). "HDAC3, one of chidamide’s targets, has been implicated in chemoresistance in various malignancies: it is essential for Kras-mutant lung cancer progression by co-regulating transcription with NKX2-1 and promoting FGFR1 expression, with its inhibition restoring trametinib sensitivity." (PMID 41326348, 2025). "Notably, HDAC3 physically associates with NKX2-1, and both C/EBP and NKX2-1 motifs are enriched at HDAC3-bound sites in Lkb1-deficient lung cancer cells." (PMID 35228570, 2022). "KDM2A suppresses histone deacetylase 3 in non–small-cell lung cancer cells, enhancing cancer cell proliferation and invasiveness by demethylating of H3K36me2 at histone deacetylase 3 promoter region." (PMID 39938867, 2025). "HDAC3-specific inhibitor has the potential to be tested for lung cancer treatment and combination chemotherapy." (PMID 30258097, 2019). "Alternatively, we proposed inhibitors of HDAC3 or knockdown of HDAC3 as chemotherapeutic strategies for lung cancer with ZNF322AHigh/c-MycLow expression." (PMID 30258097, 2019). "As an HDACi, entinostat preferentially inhibits HDAC1 as compared to HDAC3, and has been used in clinical trials to treat lung cancer patients." (PMID 27705911, 2016). "siRNA mediated knockdown of HDAC3 reduced cell proliferation with high acetylation of Dleu2/miR-15a/16-1 in the promoter region and up-regulation of miR-15a/16-1 expression in lung cancer." (PMID 25521755, 2014). "Similar to lung cancer cell lines, we found that HDAC3, HDAC9, MEF2D and GATA3 controlled BRM silencing and that HDAC9 was overexpressed in Rhabdoid cancer cell lines." (PMID 24913006, 2014). "Like lung cancer, in these Rhabdoid studies, we found that HDAC3, HDAC9, GATA3 and MEF2D regulate BRM." (PMID 24913006, 2014). "However, in lung cancer cells cytoplasmic Tip60 has been shown to be regulated by HDAC3, which prevents Tip60-dependent apoptosis." (PMID 30846725, 2019). "Thus, HDAC3i could be promising immunotherapeutic drugs to treat lung cancer patients by targeting the HDAC3-PPAR-γ axis in lung macrophage populations, which needs to be further investigated." (PMID 32732898, 2020). "Notably, ZNF322AHigh/c-MycLow expression profile in tumor specimen serves as an independent prognosis marker for poor outcome of lung cancer patients who may be considered for treatment strategy using mitochondria-targeting agents or HDAC3 inhibitors." (PMID 30258097, 2019). "The inhibition of p16INK4A promoter by HDAC3 and HDAC4 has been detected in NCI-H460 lung cancer cells." (PMID 34253688, 2021). "Importantly, ZNF322A bound directly to c-Myc promoter and recruited histone deacetylase 3 to transcriptionally suppress c-Myc expression, which in turn increased mitochondrial oxidative phosphorylation and promoted cell motility, thus maintaining stem cell-like properties of lung cancer." (PMID 30258097, 2019). "Similar to our published studies with lung cancer, we found that BRM was also regulated by HDAC3, HDAC9, GATA3, and MEF2D in Rhabdoid tumors." (PMID 24913006, 2014).
type 2 diabetes (19 papers, 2014 to 2025). "HDAC3 has also been demonstrated to improve endothelial dysfunction in type 2 diabetes mellitus (T2DM)-associated cardiovascular disease by mitigating inflammation and oxidative stress." (PMID 40258841, 2025). "In fact, in patients with type II diabetes, HDAC3 appears to be upregulated compared to other HDACs." (PMID 41369370, 2025). "Similar to our results, inhibition of HDAC3 in a mouse model of type 2 diabetes enhanced BBB permeability through activated Nrf2." (PMID 36518188, 2022). "Transcriptional profiling revealed that mRNA expression of HDAC3 was significantly (p < 0.05) increased while the Sirt1 level was significantly (p < 0.05) decreased in patients with type 2 diabetes compared to control subjects." (PMID 30139387, 2018). "Logistic regression analysis using type 2 diabetes as dependent variable showed HDAC3 activity or HDAC3 mRNA was associated significantly (p = 0.005) with T2DM, and this statistical significance was persisted even after adjusted for confounding factors like age and BMI." (PMID 27904654, 2016). "While the functional significance of alterations in HDAC1 and HDAC2 needs to be clarified in metabolic disorders, our study unraveled a consistent increase in both HDAC3 activity and HDAC3 transcriptional levels in PBMCs from patients with type 2 diabetes." (PMID 27904654, 2016). "As the highly significant HDAC3 mRNA expression was the prominent finding in our study in PBMCs from patients with type 2 diabetes, we then analyzed the specific HDAC3 activity in the study samples." (PMID 27904654, 2016). "Also, HDAC3 inhibition improved pancreatic β cell function and plasma glucose levels in a rat model of type 2 diabetes." (PMID 39050859, 2024). "Moreover, HDAC3 inhibition has also been shown to improve plasma glucose levels and pancreatic β cell function in a rat model of type 2 diabetes." (PMID 31101061, 2019). "In conclusion, in this study we provide additional evidence that HDAC3 could also be a potential drug target for preserving pancreatic beta cells against apoptosis induced by lipotoxicity in type 2 diabetes." (PMID 25610877, 2014). "Contrary to the reported study showing up-regulation of HDAC3 RNA level in Type 2 diabetes patients, we did not observe significant changes in HDAC3 at the protein level." (PMID 32152128, 2020). "As we saw a negative correlation between HDAC3 activity and mRNA levels of DBC1 in our study, it appears that the regulatory circuit of endogenous control of HDAC3 could be somehow lost in patients with type 2 diabetes and this needs to be studied in-depth in future investigations." (PMID 27904654, 2016).
liver cancer (18 papers, 2018 to 2025). An epithelial or non-epithelial malignant neoplasm that arises from the liver. "In summary, our study, for the first time, reports that HDAC3 deficiency leads to a higher incidence and earlier onset of liver cancer in female mice." (PMID 37752418, 2023). "Loss of HDAC3 expression in liver cancer stem cells decreases the expression of stem cell markers, including Nanog, OCT4, and SOX2." (PMID 29301348, 2018). "Herein, differently to what described in liver cancer cells, HDAC3 depletion alone is ineffective in inducing phosphorylation of H2AX (i.e., γH2AX), a marker of DNA damage, but highly enhances IR-induced γH2AX increase." (PMID 39107280, 2024). "As one of the most important HDACs for regulating the cell cycle, HDAC3 participated in developing liver cancer in mice; when HDAC3 is deleted can result in a significant loss of genomic stability as well as tumorigenesis." (PMID 38637684, 2024). "HDAC3 is highly expressed in liver cancer, and silencing HDAC3 inhibits both the proliferation and self-renewal of liver CSCs." (PMID 37743465, 2023). "More notably, HDAC3 knock‐down also significantly inhibited sphere formation of Huh7 cell line and primary liver cancer cells upon glutamine starvation, suggesting that HDAC3 activity is critical to regulate the self‐renewal of TICs under glutamine starvation." (PMID 35187863, 2022). "TKT then inhibits the expression of the farnesoid receptor (FXR) (a tumor suppressor gene) by promoting the binding of histone deacetylase-3 (HDAC-3) to the FXR promoter, causing increases in intrahepatic bile acid (related to the occurrence of liver cancer)." (PMID 33520706, 2020). "Consistently, HDAC3 knockdown in human liver cancer cells HepG2 using siRNA significantly increased ac-STAT3 expression level and remarkably inhibited cell growth." (PMID 29540666, 2018). "Here, we have established for the first time the importance of HDAC3 for liver regeneration together with liver cancer cells proliferation." (PMID 29540666, 2018). "HDAC3 is expressed in liver cancer stem cells and is required for the self-renewal of liver cancer stem cells." (PMID 29301348, 2018). "HDAC3 inhibition induces G1 phase arrest by increasing p21WAF1/cip1 expression in Hep3B liver cancer cells." (PMID 29540666, 2018). "In this study, we determined that HDAC3 promotes liver regeneration and liver cancer cells proliferation through the signal transducer and activator of transcription 3 (STAT3) signaling pathway." (PMID 29540666, 2018). "Inhibition of HDAC3 expression reduced liver cancer cells growth and inhibited xenograft tumor growth." (PMID 29540666, 2018). "We speculate that the activity of HDAC1 and HDAC3 may be related to other phenotypes of liver cancer." (PMID 33718133, 2021). "Moreover, inhibited xenografted tumor growth in liver cancer is partially ascribed to HDAC3 inhibition." (PMID 33203425, 2020). "However, the biological function of HDAC3 in liver regeneration and liver cancer cells proliferation remains unknown." (PMID 29540666, 2018). "Therefore, increased HDAC3 enhanced tumor growth that may occur through STAT3 signaling in liver cancer cells." (PMID 29540666, 2018). "To further elucidate that HDAC3 controls the expression of Foxa1/2, we knocked down HDAC3 in HUH7 liver cancer cells." (PMID 37752418, 2023). "It was found that a lack of HDAC3 decreases the phosphorylation of STAT3 at Y705 in liver cancer and multiple myeloma." (PMID 37743465, 2023). "Moreover, when HDAC3 was knockdown in liver cancer cells, glutamine deprivation did not increase the protein level but did increase the acetylation and polyubiquitination of GS, suggesting that HDAC3 as a major deacetylase determined the deacetylation and stability of GS." (PMID 35187863, 2022).